KLF4 (KLF transcription factor 4)
Diseases named in the same sentence as KLF4 in open-access papers (continued):
Sharing a sentence is not in itself a finding about the gene and the disease.
atherosclerosis (continued). "Moreover, in an atherosclerosis mouse model, Nox1 and KLF4 were significantly downregulated in the ANGPTL4 group." (PMID 36782020, 2023). "Current studies have shown that KLF4 has many roles, such as inhibiting and promoting tumour progression, regulating the cell cycle, influencing macrophage polarization, regulating the inflammatory response, and affecting atherosclerosis." (PMID 36419827, 2022). "Antcin K not only reduced the expression of the CD36 scavenger receptor but also augmented the expression of Kruppel-like factor 4 (KLF4) transcription factor in macrophages, which inhibits the transformation of macrophages into foam cells underlying the pathological process of atherosclerosis." (PMID 36365265, 2022). "However, the KLF4 expression trends of different VSMC phenotypes through atherosclerosis progression and potential role of KLF4 at late stage of macrophage-like VSMC are shortage of evidence from in vivo tests." (PMID 36456628, 2022). "KLF4-induced phenotypic switching of vascular smooth muscle cells occurs in atherosclerosis." (PMID 36470917, 2022). "The Kruppel-like factor 4 (KLF4) transcription factor may play a key in regulating macrophage activation that is involved in the formation and progression of atherosclerosis." (PMID 36365265, 2022). "In addition, previous studies have shown that knockout of KLF4 alleviates the development of atherosclerosis by inhibiting the phenotypic switching of vascular smooth muscle." (PMID 34102609, 2021). "KLF4 is an important transcription factor of VSMCs phenotypic transformations, macrophage polarization, lymphocyte differentiation, and cell proliferation as atherosclerosis progression." (PMID 34211091, 2021). "For example, deletion of Klf4 in perivascular smooth muscle cells (pvSMCs) within large arteries led to reductions in atheroma formation, however deletion of Klf4 in endothelial cells significantly increased atherosclerosis progression in mice fed a high-fat diet." (PMID 33266506, 2020). "Noticeably, KLF4 plays an important role in atherosclerosis." (PMID 31938053, 2020). "As angiogenesis and maintenance of vascular tone are critical for malignancy, these findings suggest that KLF4 may impact not only on atherosclerosis, but more generally, on blood vessel homeostasis." (PMID 33266506, 2020). "Noticeably, activation of AMPK can modulate the expression of KLF4 37 and inhibit atherosclerosis." (PMID 31938053, 2020). "Our data shows a novel evolutionary-conserved role of flow-driven KLF4-dependent Cx40 expression in endothelial quiescence that may be relevant for the control of atherosclerosis and diseases involving sprouting angiogenesis." (PMID 30809154, 2019). "It seems that KLF4 will be a critical target for macrophage skewing and activating KLF4 may benefit atherosclerosis regression." (PMID 30923552, 2019). "Additionally, KLF4 knock-out in an atherosclerosis animal model revealed the switch of VSMCs toward a synthetic phenotype, while suppressing the macrophage-like form." (PMID 31739395, 2019). "Conversely, endothelial-driven overexpression of Klf4 is protective against atherosclerosis." (PMID 29459900, 2018). "While the role of KLF4, a regulator of pro-inflammatory signaling in the heart, has been well established in the development of vascular disease including atherosclerosis, a recent study has also shown that KLF4 is important in regulating cardiac hypertrophy and cardiac mitochondrial homeostasis." (PMID 28850583, 2017). "Furthermore, a role for miR-92a-dependent regulation of KLF2/KLF4 in the pathogenesis of atherosclerosis was recently demonstrated." (PMID 25540650, 2014). "Based on the established roles of SENP3 in regulating key signaling molecules and the critical function of KLF4 in VSMC biology, we hypothesize that SENP3 promotes VSMCs phenotypic switching and atherosclerosis progression through deSUMOylation and stabilizing KLF4." (PMID 41307849, 2025).
atherosclerosis (continued). "This resulted in the phenotypic transition of VSMCs from a contractile to a synthetic state and increased plaque area by 47.4% and heightened plaque instability, indicating that targeting Fam172a or KLF4 using gene therapy may offer a new therapeutic approach for atherosclerosis." (PMID 41373858, 2025). "In addition, TET2 may affect the regulation of KLF4, a gene involved in phenotypic switching of vascular smooth muscle cells, a process central to the pathology of atherosclerosis." (PMID 40428388, 2025). "Our results demonstrate that manipulating the key proteins that regulate cholesterol esterification and cholesterol efflux through the downregulation of FASN and KLF4 displays a trend that could increase cholesterol efflux and result in a slower progression of atherosclerosis." (PMID 38667273, 2024). "Moreover, global DNA hypomethylation is observed in atherosclerotic lesions both in humans and in animal models, whereas the promoter regions of atherosclerotic protective genes such as estrogen receptor β, ABCA1 and Krüppel-like factor 4 (KLF4) are often hypermethylated in atherosclerosis." (PMID 37762023, 2023). "Furthermore, epigenetic changes were also identified in several genes including RELA (RELA Proto-Oncogene, NF-KB Subunit), NOS3 (Nitric Oxide Synthase 3), KLF4 (KLF Transcription Factor 4) and APOE (Apolipoprotein E) that have been linked to progression of atherosclerosis." (PMID 37190071, 2023). "Decreased KLF4 activity alters the expression of its downward transcription targets, such as decreased nitric oxide synthase 3 and thrombomodulin, and increased monocyte chemoattractant protein‐1, making the vascular environment prone to inflammation and atherosclerosis." (PMID 36807865, 2023). "Besides, KLF4 was found to cooperate with Stat6 to induce an M2 genetic program and inhibit M1 targets via sequestration of coactivators required for NF-κB activation, which suggested KLF4 to be a novel regulator of macrophage polarization and the treatment of atherosclerosis." (PMID 32065217, 2020). "Moreover, miR-103-induced silencing of lncWDR59 may mediate the effect of endothelial Dicer on disturbed flow-induced EC proliferation and hyperlipidemia-induced EC injury and, together with the targeting of Klf4, promote atherosclerosis." (PMID 29980665, 2018). "Moreover, selective inhibition of the targeting of KLF4 by miR-103 using antisense oligonucleotides may represent a novel approach to treat atherosclerosis." (PMID 26837267, 2016). "Other VSMC-specific targets, including transcription factor 21, hyaluronan synthase 3, KLF4, growth differentiation factor 10, and NOTCH, offer potential therapeutic avenues for atherosclerosis, including in diabetes." (PMID 40076813, 2025). "The multi-functional transcriptional regulator and pluripotency factor Krüppel-like factor 4 (KLF4) acts as a gatekeeper of VSMC phenotypic switching and MØ polarization during vascular inflammation and atherosclerosis." (PMID 41155497, 2025). "Recent studies indicate that atheroprotective shear stress induces HEG1-mediated KLF2 and KLF4 expression, and endothelial HEG1 is downregulated in individuals with advanced atherosclerosis." (PMID 40172727, 2025). "KLF4 is a well-established master regulator of VSMC plasticity, and its genetic ablation in VSMCs attenuates atherosclerosis and aortic aneurysm formation." (PMID 41307849, 2025). "In MØ, on the other hand, interplay of KLF4, STAT, IRF, and NF-κB has both pro- and anti-inflammatory outcomes connected to atherosclerosis." (PMID 41155497, 2025). "In the vascular system, KLF4 has been established as a central mediator of VSMC plasticity; its genetic deletion in smooth muscle cells significantly attenuates atherosclerosis and aortic aneurysm formation in murine models." (PMID 41307849, 2025). "KLF4 responds to both USS and OSS, attenuating atherosclerosis by suppressing TGF-β activity, which is mediated by the MEKK3/MEK5/ERK5/MEF2 cascade activation." (PMID 41373858, 2025).
atherosclerosis (continued). "The multi-functional transcriptional regulator and pluripotency factor KLF4 acts as a gatekeeper of VSMC phenotypic switching and MØ polarization during vascular inflammation and atherosclerosis." (PMID 41155497, 2025). "KLF4 acts as a multi-functional transcriptional regulator of VSMC phenotypic switching and MØ polarization, inflammation, and progression of atherosclerosis." (PMID 41155497, 2025). "Regarding the impact of abnormal DNA methylation on inflammation and endothelial dysfunction in atherosclerosis, key protective factors such as KLF2, KLF4, and CREG exhibit anti-atherosclerotic actions." (PMID 40428388, 2025). "Early investigations (2005–2010) established fundamental connections between DNA methylation patterns and atherosclerosis development, particularly the silencing of protective genes such as KLF2 and KLF4 through promoter hypermethylation." (PMID 40428388, 2025). "In our research, we revealed that EEPD1 is elevated in atherosclerosis and enhances ERK phosphorylation while deteriorating endothelial function and apoptosis; these impacts are further intensified by KLF4 suppression." (PMID 40268512, 2025). "The results revealed that, compared to the ND group, the HFD group exhibited conspicuous co-localization of α-SMA+CD68+KLF4+, α-SMA+CD68+p-JAK2+, and α-SMA+CD68+p-STAT3+ at the foam cell aggregation regions of atherosclerosis plaque-rich aortic." (PMID 39062998, 2024). "A similar expression pattern is visible in other inflammation and atherosclerosis related genes such as APOE, KLF4, CXC3L1, STC1, CH25H, and ABCG1." (PMID 39695567, 2024). "Given the pivotal role of this phenotypic switch in the pathogenesis of atherosclerosis, it is crucial to identify effective therapeutic agents that target the JAK2/STAT3/KLF4 pathway to inhibit the transition of VSMCs to macrophage-like cells." (PMID 39062998, 2024). "MiRNA 103 is believed to play a role in cardiomyocyte necrosis and atherosclerosis through activation of FADD and by suppression of KLF4." (PMID 37438691, 2023). "SMC phenotypic switching is a key phenomenon underlying several vessel-narrowing diseases, such as atherosclerosis, and our study showed that ANGPTL4 could be a potential regulator of SMC differentiation by blocking the transition to macrophage-like cell types by downregulating KLF4." (PMID 36782020, 2023). "Although KLF4 positively regulates OCT4 in SMC, we observed that the genetic inactivation of KLF4 and OCT4 in SMC resulted in opposite effects on atherosclerosis development." (PMID 37942066, 2023). "In the setting of atherosclerosis, miR-126 promotes macrophage polarization to the M2 phenotype by downregulating VEGFA and krüppel-like factor 4 (KLF4)." (PMID 38026969, 2023). "KLF4 and BCLAF1 initiate SMC phenotypic switch in atherosclerosis by inducing SMC lipid transdifferentiation, whereas KLF11 has been shown to inhibit arterial thrombosis." (PMID 36188622, 2022). "In mice, genetic deficiency of either KLF2 or KLF4 in ApoE-/- mice (which develop atherosclerotic lesions when placed on high fat diet) enhances atherosclerosis, indicating an atheroprotective role for KLF2 and KLF4." (PMID 25540650, 2014). "Our results unveil a VSMC-specific atheroprotective role for KIF13B, define the KIF13B/KCTD10/KLF4 pathway as a key regulatory axis governing VSMC fate and plaque stability, and validate the therapeutic potential of KIF13B for treating advanced atherosclerosis." (PMID 41609725, 2026). "Moreover, in the HFD ApoEKO mouse atherosclerosis model, VSMC-specific conditional KO of KLF4 resulted in reduced lesion size, increased fibrous cap thickness, and major reductions in the fraction of VSMC-derived MØ- and MSC-like cells." (PMID 41155497, 2025). "Beyond KLF2 and KLF4, other KLF members contribute to atherosclerosis management." (PMID 41373858, 2025).
atherosclerosis (continued). "KLF4 also exerts a crucial influence on many cardiovascular disorders, namely, atherosclerosis, cardiac hypertrophy, nonischemic cardiomyopathy, and myocardial ischemia‐reperfusion." (PMID 40268512, 2025). "While many immune pathways were enriched in the upregulated DEGs (e.g., CXCR5, IL21R, CCR7 and CD22) (A,C), pathways such as “lipid and atherosclerosis’ and “fluid shear stress and atherosclerosis” were enriched in the downregulated DEGs (such as NOS3, KLF2 and KLF4)." (PMID 37218991, 2023). "While we anticipated that KO of Klf4 specifically in AdvSca1-SM cells would alter their differentiation patterns during atherosclerosis progression, we also observed substantial shifts in the phenotype of YFP– non–AdvSca1-SM–derived cell populations in response to AdvSca1-SM cell Klf4 KO." (PMID 37991018, 2023). "Consequently, antcin K decreased CD36 expression and increased KLF4 expression, which enhanced oxidized LDL efflux in macrophages, alleviated lipid deposition, and decreased atherosclerotic lesions, thereby reducing atherosclerosis formation." (PMID 36365265, 2022). "Consistent with a proposed role of ERK5, KLF2, and KLF4 in atheroprotection, various mouse models of atherosclerosis further established a key role of the ERK5/KLF2/KLF4 cascade as a flow-regulated signaling module that safeguards from atherosclerosis." (PMID 34299213, 2021). "As KLF4 synergized with CREB in atherosclerosis and co-regulated the renal progenitor cell proliferation with PACAP 52, we then asked whether KLF4 contributed to the regulation of PACAP-CREB axis in our model." (PMID 32292507, 2020). "Moreover, KLF4 activates > 800 pro-inflammatory VSMC genes, of which many are atherosclerosis relevant." (PMID 31739395, 2019). "Exposure of peritoneal macrophages to an inflammatory lipid reduces Klf4 and increases M1 mRNAs, the latter induced to a greater extent in Klf4(f/f);Lys-Cre macrophage, and absence of myeloid Klf4 augments atherosclerosis in ApoE-/- mice." (PMID 29324844, 2018). "However, prolonged intervention of KLF4 may lead to abnormal proliferation of VSMC or differentiation imbalance, thus contributing to the progression of atherosclerosis, hypertension, or vascular wall thickening." (PMID 41373858, 2025). "Of note, KLF4 may induce positive or negative effects of senescence during atherosclerosis because it exhibits dual regulation of protein expression through direct DNA binding." (PMID 38728249, 2024). "In the mouse atherosclerosis model, SMC-specific KLF4 knockout showed less mesenchymal-stem-cell- and macrophage-like cells derived from SMC, along with less lesion and increased fibrous cap thickness, underscoring significant roles of KLF4 in the cardiovascular diseases." (PMID 38247859, 2024). "This anti-atherosclerotic effect of CTRP9 may be partly attributed to the inhibition of HG-induced endothelial senescence through an AMPKα/KLF4-dependent mechanism, suggesting that CTRP9 could benefit further therapeutic approaches for type 2 diabetes mellitus‒accelerated atherosclerosis." (PMID 34744738, 2021). "Extracellular atherosclerosis plaque proteins in myeloid cells lacking Klf4*." (PMID 29324844, 2018). "KLF4 induces the expression of cholesterol-25-hydroxylase (Ch25h) and liver X receptor (LXR) in ECs, which contribute to reverse cholesterol transport out of the vascular wall and inhibition of endothelial inflammasome activation, both protective against atherosclerosis." (PMID 29459900, 2018). "Current research further proposes that miR-145 or miR-143 are part of the regulatory loop for KLF-4, KLF-5, MYOCD, and SRF; critical transcription factors the development of SMC phenotype, and lacking SMC correct differentiation could lead more easily to the development of atherosclerosis." (PMID 36836777, 2023). "Unlike KLF2 and KLF4, KLF5 aggravates atherosclerosis via non-coding RNAs networks, including miRNAs, lncRNAs, and circRNAs." (PMID 41373858, 2025).
atherosclerosis (continued). "However, the potential regulation of KLF4 by SENP3, and functional consequences of such regulation in VSMCs and atherosclerosis, have not been explored." (PMID 41307849, 2025).